PTPRD-AS1 (PTPRD antisense RNA 1)
Gene: Long non-coding RNA gene on chromosome 9 (8,857,982 to 8,864,772, forward strand). Ensembl gene ENSG00000225706.
Diseases named in the same sentence as PTPRD-AS1 in open-access papers:
PTPRD-AS1 is named in the same sentence as 1 disease in open-access papers, as found by Europe PMC text mining. Sharing a sentence is not in itself a finding about the gene and the disease.
PTPRD-AS1 shares sentences with these, for which no sentence is quoted: cancer (1 paper).